CSF1 (colony stimulating factor 1)
Diseases named in the same sentence as CSF1 in open-access papers (continued):
Sharing a sentence is not in itself a finding about the gene and the disease.
breast cancer (continued). "In breast cancer tissues from MMTV-PyMT mice, a developmental model of breast cancer, CSF-1 expression by cancer cells leads to TAM infiltration via CSF-1 receptor signaling." (PMID 40940867, 2025). "Invasive tumor cells and macrophages have been found to co-migrate in primary mammary tumors of mice and rats only in response to EGF and CSF-1; thus, blockade of either EGF receptor or CSF-1 receptor signaling blocks migration of both cell types in vivo." (PMID 39003350, 2024). "Thus, the co-expression of CSF-1 and the CSF-1R in cancer cells suggests both autocrine and paracrine mechanisms driving tumor invasion and metastasis as the CSF-1R is highly expressed by TAMs, emphasizing the prognostic value of TAMs, and in turn of the CSF-1R, in breast cancer." (PMID 39457693, 2024). "Under hypoxic conditions, hypoxia-inducible factor 1 α (HIF-1α) can synergize with chemokine signals from mesenchymal stem cells to trigger colony-stimulating factor 1 (CSF-1) and chemokine receptor type 5 (CCR5) gene transcription in breast cancer cells." (PMID 39192979, 2024). "High expression levels of CSF1 and CSF1R were related to breast cancer progression and poor prognosis." (PMID 37097499, 2023). "Monocytes recruited by colony stimulating factor 1 (CSF1) and chemokine (C-C motif) ligand 2 (CCL2) secreted by breast cancer cells can develop into TAMs under various tumor microenvironmental signals." (PMID 36674955, 2023). "CSF1 activates its receptor (CSF1R) and subsequently activates PI3K and ERK signaling in HER2+ breast cancer cells." (PMID 38028209, 2023). "Elevated levels of circulating CSF1, a proliferation and survival factor for monocytes and macrophages, have been reported at late stages of cancer in the spontaneous FVB PyMT model of breast cancer as well as in human cancers." (PMID 35159100, 2022). "In breast cancer, FERMT2 regulates tumor growth through promoting CSF-1-mediated infiltration of macrophages." (PMID 36480537, 2022). "To address this, we first focused on genes that were downregulated upon CRISPRi inhibition of the CSF1 TSS and calculated hazard ratios (HRs) using the Cox proportional hazards model for each gene using the METABRIC breast cancer dataset." (PMID 35406623, 2022). "Perivascular macrophages respond to CSF-1 by proliferating and secreting EGF, which in turn further activates breast cancer cells." (PMID 36436127, 2022). "Recently, one study showed that treating breast cancer with Paclitaxel can increase macrophage chemotactic factors such as CCL8, IL-34, CSF-1, and CSF-1 receptors in vivo to enhance TAM migration." (PMID 34207035, 2021). "In line with this, the genetic ablation of CSF-1 reduced macrophage density and slowed tumor progression and metastasis in the MMTV-PyMT model of breast cancer." (PMID 33968034, 2021). "CD209, CD163, CSF1, and MMD were related to M2 macrophage proportions in cutaneous melanoma, breast carcinoma, head and neck squamous cell carcinoma, hepatocellular carcinoma, prostate cancer, renal cancer, and lung adenocarcinoma." (PMID 33828973, 2021). "Through CSF1-EGF interactions, invadopodia and podosome were formed in breast cancer cells and TAMs, respectively, thus promoting ECM breakdown and intravasation." (PMID 32726950, 2020). "Invasive tumor cells can migrate together with macrophages in primary mammary tumors in response to EGF and colony-stimulating factor 1 (CSF-1), which can be blocked by inhibiting either EGFR or CSF-1 signaling." (PMID 32883032, 2020). "In breast cancer, a reciprocal paracrine loop between macrophages and cancer cells, involving EGF, CSF-1, CSF-2 or CCL18, led to the epithelial to mesenchymal transition (EMT), increased cell motility, invasion and metastasis." (PMID 31142340, 2019).
breast cancer (continued). "Dovitinib (TKI258, Novartis) is an example of a non-selective inhibitor of FGFR family showing high potency for c-KIT, CSF-1, VEGFR and PDGFR which has been tested in six Phase I/II clinical trials involving advanced breast cancer patients." (PMID 31142340, 2019). "Breast cancer TAMs express CCL8, which is chemotactic for monocytes and drives a positive regulatory loop between cancer cells and TAMs through CSF1 and TNF-α, which upregulates SIGLEC1." (PMID 30930117, 2019). "Next, we examined the prognostic effect of CSF-1, CSF-1R, PTPRZ1, and syndecan-1 expression in the breast cancer TCGA dataset by generating Kaplan–Meier survival curves split in high (top 50%) and low (bottom 50%) gene expression." (PMID 29796177, 2018). "We used the ESTIMATE algorithm to correlate the extent of stromal cells with expression of IL-34, CSF-1, CSF-1R, PTPRZ1, and syndecan-1 in breast cancer tissue from the TCGA breast cancer dataset." (PMID 29796177, 2018). "For example, genetic ablation of colony‐stimulating factor 1 (CSF1), an important factor for macrophages, in the MMTV‐PyMT breast cancer mouse model delayed progression of mammary tumors to malignancy." (PMID 28028012, 2017). "The overexpression of macrophage colony-stimulating factor (CSF-1) and its receptor (CSF1-R) has been correlated to poor prognosis in human breast carcinomas." (PMID 28567162, 2017). "Although NCOA1 is known to promote breast cancer metastasis through working with multiple transcription factors to upregulate the expression of Twist1, ITGA5, CSF-1, SDF1 and CXCR4, the role of NCOA1 in breast tumor angiogenesis has not been investigated." (PMID 26287601, 2015). "CSF-1 expression in metastatic tumor cells can stimulate OCL activity and can enhance osteolysis in breast cancer metastasis." (PMID 25147739, 2014). "These FOTS+/TGCT/CSF1+ breast cancers were also more likely to be Basal subtype (17 in 34), while FOTS-/TGCT/CSF1- breast cancers were more likely to be Luminal A subtype (94 in 270)." (PMID 24342436, 2013). "The EF and the previously identified DTF fibroblast signature both identify good outcome in breast cancer, while the FOTS and the previously identified TGCT/CSF1 macrophage signature both identify bad outcome in breast cancer." (PMID 24342436, 2013). "FOTS+/TGCT/CSF1+ breast cancers are more likely to be ER-/PR-, high grade, base-like breast cancers than FOTS-/TGCT/CSF1- breast cancer cases." (PMID 24342436, 2013). "In breast carcinomas, macrophages and cancerous cells form a paracrine loop involving epidermal growth factor (EGF) and colony stimulating factor-1 (CSF-1) to augment chemotaxis and intravasation." (PMID 22482059, 2012). "Coordinated expression of CSF-1 in macrophages and epidermal growth factor (EGF) in mammary tumor cells resulted in increased myeloid cell invasion into mammary tumors." (PMID 20490273, 2010). "Inhibition of TAM recruitment and survival by targeting CSF-1 and CD115 in breast cancer models has a significant effect on tumor development." (PMID 19522014, 2009). "In the absence of CSF-1, the formation and growth of primary mammary tumors were not altered, but the recruitment of macrophages and both the progression to malignant forms and lung metastasis of tumor cells were significantly delayed." (PMID 37208442, 2023). "Thus, blocking CSF-1 or EGF receptors reduces cancer cell migration and invasiveness in breast cancer rodent models." (PMID 37429944, 2023). "By targeting CSF1, miR-149 inhibits CSF1 dependent communication between TNBC cells and THP-1 macrophages, thereby blocking the paracrine interactions between MDA-MB-231 cells and THP-1 cells and inhibiting breast cancer metastasis." (PMID 37122564, 2023). "In breast cancer, the inhibition of SPP1 and CSF1 could prevent the assembly of an immunosuppressive tumor microenvironment and partially or completely sensitize otherwise refractory quasi-mesenchymal tumors to anti-CTL4 immune checkpoint blockade therapy." (PMID 37097499, 2023).
breast cancer (continued). "But the results are contradictory; in a recent breast cancer clinical trial, the use of neutralizing anti-CSF1R and anti-CSF1 antibodies, along with the small-molecule inhibitors of CSF1R, showed an enhancement in the metastasis without altering primary tumor growth." (PMID 37279073, 2023). "Besides, c-MYC mRNA was significantly upregulated in macrophages after CSF-1 stimulation, boosting macrophage proliferation.Via JAK1/STAT3 signaling pathway, IL-11 induces c-MYC expression to promote breast cancer bone metastasis." (PMID 36721232, 2023). "In breast cancer, carcinoma cells express epithelial growth factor receptor (EGFR), which, after activation, promotes invasion and migration, and induces secretion of colony-stimulating factor-1 (CSF-1), the main chemoattractant and activator of macrophages." (PMID 36436127, 2022). "While H3K27ac signal is present in other breast cancer subtypes at this site, we found that eRNA transcription is specific to TNBC cells and correlates with increased expression of its nearest neighboring gene, CSF1." (PMID 35406623, 2022). "Interestingly, we found that ovarian cancer was among the highest in CSF1 mRNA expression (RSEM) and even surpassed breast cancer." (PMID 35406623, 2022). "CSF-1 stimulation increased spp1 gene expression only in the C3-223-Fms mammary cancer cells but not in the NIH 3T3." (PMID 36555673, 2022). "Furthermore, the colony stimulating factor (CSF)-1 inhibitor reduces tumor growth and progression and prolongs survival by suppressing TAM infiltration in mouse mammary cancers." (PMID 36555393, 2022). "Moreover, CSF1 (and CSF1R) expression has been shown to correlate with progression and clinical outcome in breast cancer, making this enhancer an interesting candidate for further study." (PMID 35406623, 2022). "Together, these results showed that spp1/osteopontin is a target gene of the CSF-1/CSF-1R axis in both prostate and breast cancer cells but not in the NIH3T3 fibroblast cell line." (PMID 36555673, 2022). "TAMs are recruited to mammary tumors through induction of a variety of cytokines and chemokines including C-C Motif Chemokine Ligand 2 (CCL2), CCL3, CCL5, Colony Stimulating Facotor-1 (CSF-1/M-CSF), and Granulocyte-Macrophage Colony-Stimulating Factor (GM-CSF or CSF2)." (PMID 34298673, 2021). "Since IV2 was derived from human breast cancer cell line, MDA-MB-231, we further examined whether human CSF1 (hCSF1) can stimulate mouse CXCL7 (mCXCL7) secretion in bone marrow-derived mouse monocytes." (PMID 34789744, 2021). "In two breast cancer models, CSF1 neutralization increases spontaneous metastasis without altering primary tumor growth in mice." (PMID 32801364, 2020). "CSF-1 stimulation significantly enhanced cell migration in MCF-7 breast cancer cells by 52%, while no significant increases were observed for SK-BR-3 (7%; n.s) and MDA-MB-231 (10%; n.s) relative to control cells." (PMID 29796177, 2018). "In a mouse model of spontaneous breast cancer, researchers showed that genetic ablation of CSF-1 does not affect primary tumor incidence or growth, but strongly inhibits the development of metastases through a reduction in TAMs." (PMID 30355585, 2018). "Thus, we analyzed potential mRNA expression differences of CSF-1, CSF-1R, PTPRZ1, and syndecan-1 between breast cancer samples and normal breast tissue samples from the TCGA breast cancer dataset." (PMID 29796177, 2018). "Moreover, among the significantly reduced secreted proteins we found the colony-stimulating factor 1 (CSF1), in agreement with previous data in MTLn3 mammary tumors reporting that increased MENA11a expression correlates with decreased expression of CSF1." (PMID 29907768, 2018). "Together with the observed low CSF-1R activation in breast cancer cells, we hypothesize that IL-34 and its receptor PTPRZ1 directly regulate cancer cells, whereas CSF-1/CSF-1R are primarily involved in regulation of stromal and immune cells." (PMID 29796177, 2018).
breast cancer (continued). "Additionally, inhibition of CSF1 using either an antisense oligonucleotide or anti-CSF1 antibody suppresses macrophage recruitment and results in reduced tumor growth in human MCF-7 breast cancer cell–xenografted mice." (PMID 28467800, 2017). "While high levels of CSF-1 were often observed in luminal breast cancer cells, CSF-1 is not frequently overexpressed by pancreatic cancer cells." (PMID 27191744, 2016). "Our research study also proved that metastatic breast cancer cells secrete more CSF-1 as compared to non-metastatic breast cancer cells." (PMID 26557105, 2015). "To study whether ectopically expressed Vav1 in breast cancer cells is functionally active, we stimulated MCF-7Vector and MCF-7Vav1 cells with EGF and AU565Vector and AU565Vav1 with CSF1 for various time intervals." (PMID 23342133, 2013). "This is consequential, because recruitment of CCR2 positive inflammatory Mø has been shown to occur preferentially in the lung pre-metastatic niche rather than in the primary mammary tumors of late-stage PyMT-induced breast cancers, which instead recruit CCR2-negative, CSF-1 dependent TAMs." (PMID 23372702, 2013). "shEGFR-MDA-231 cells also produced decreased levels of the proangiogenic molecules macrophage colony stimulating factor-1 (MCSF-1) and matrix metalloproteinase 9 (MMP9), both of which were decreased by EGFR inhibitors in a panel of EGFR-positive breast cancer cells." (PMID 22276166, 2012). "Additionally, invasive breast cancer cells, MDA-MB-231, undergo metastasis in vivo based on the communication between their secreted factors, colony stimulating factor-1 (CSF-1) and EGF, which are growth factors released by surrounding macrophages." (PMID 22174624, 2011). "Moreover, gene expression profiling datasets show that CSF1 and CSF1R expression is a general feature of breast cancer cells." (PMID 22096574, 2011). "Macrophages can modulate breast cancer metastasis, with mice lacking colony-stimulating factor-1 (CSF-1), a macrophage-stimulating factor, showing reduced tumour metastasis in a mouse model of breast cancer." (PMID 19077226, 2008). "In both B16/F10 melanoma and 4T1 breast cancer models, the supramolecule demonstrated robust anti-tumor and anti-metastatic efficacy, suggesting that the simultaneous blockade of the CD47/SIRPα and CSF-1/CSF-1R signaling axes can be further explored as a potent immunotherapeutic strategy." (PMID 39457693, 2024). "SRC-1 may contribute to the metastatic activity of breast cancer by promoting Ets2-mediated HER2 expression and promoting the recruitment of macrophages to tumour sites by upregulating the expression of colony-stimulating factor 1 (CSF-1)." (PMID 38553750, 2024). "Furthermore, ALKBH3 was also reported to promote ovarian and breast cancer invasiveness by demethylating m1A and stabilizing the colony-stimulating factor 1 (CSF1) mRNA without affecting cell proliferation or migration." (PMID 37612540, 2023). "A pivotal investigation utilizing the MMTV-PyMT mouse model for breast cancer revealed that the absence of colony stimulating factor 1 (CSF-1), a factor necessary for the growth of CSF-1-dependent cells like monocytes and macrophages, led to slower transition of mammary tumors into metastasis." (PMID 37440925, 2023). "During cancer progression, C-C motif chemokine ligand 2 (CCL2) and colony-stimulating factor 1 (CSF1) recruit and maintain macrophages in the TME, and CSF1-recruited TAMs express TFs, including Ets2, to promote angiogenesis, tumor growth, and breast cancer metastasis." (PMID 36248881, 2022). "Pexidartinib (PLX3397) is a small molecule tyrosine kinase and colony-stimulating factor-1 inhibitor with FDA breakthrough therapy designation for tenosynovial giant-cell tumor, and currently under study in several other tumor types, including breast cancer, non-Hodgkin's lymphoma, and glioblastoma." (PMID 31240240, 2019).
breast cancer (continued). "To experimentally evaluate, whether IL-34 and CSF-1 directly regulate breast cancer cells depending on their subtype, we assessed the effect of recombinant IL-34 and CSF-1 on luminal-like MCF7, HER-2-positive SK-BR-3, and basal type MDA-MB-231 breast cancer cells." (PMID 29796177, 2018). "In this article, correlative analysis of IL-34 expression and breast cancer prognosis stratified by PAM50 tumor subtype showed an unexpected prognostic relationship between intrinsic subtype and overall survival that demonstrated patterns contrasting previous studies analyzing CSF-1 and CSF-1R." (PMID 29796177, 2018). "NCOA1 has previously been reported to be overexpressed in breast cancer and its increased expression positively correlated with disease recurrence and metastasis through working with multiple transcription factors to, in turn, upregulate the expression of Twist1, ITGA5, CSF-1, SDF1 and CXCR4." (PMID 28060733, 2017). "Inhibition of colony-stimulating factor-1 (CSF-1, also known as M-CSF), the primary regulator of tissue macrophage production, or the blockade of CSF-1 receptor (also known as CD115 or c-fms) led to decreased macrophage infiltration and less mammary tumor growth." (PMID 28197019, 2017). "Moreover, in silico analysis of comparative genomic hybridization datasets relative to 49 breast cancer cell lines and 67 primary tumors indicated the absence of CSF-1R or CSF-1 gene amplifications." (PMID 22096574, 2011). "Thus CXCR4 overexpression did not override the dependency of these breast cancer cells on the EGF/CSF-1 paracrine loop for in vivo invasion." (PMID 22152016, 2011). "Multifocal mammary tumors arise and progress steadily to pulmonary metastasis in the female mice and, while initiation and early progression of mammary tumors are unchanged, late stage progression is slowed and pulmonary metastasis is all but halted in the absence of CSF-1-dependent TAMs." (PMID 39588367, 2024). "To determine if the activity of the enhancer might be contributing to the increased CSF1 expression in TNBC tumors, we analyzed The Cancer Genome Atlas (TCGA) ATAC-seq data to compare the chromatin accessibility landscape of this enhancer across 133 breast cancer samples." (PMID 35406623, 2022). "Similarly, MDA-MB-468 breast carcinoma cell and metastatic CL16 cancer cells, which are derived from MDA-MB-435 cells, also demonstrated decreased CSF-1 gene expression when switched from normoxic to hypoxic conditions, suggesting that this response may be widespread amongst various types of cancer." (PMID 19696929, 2009). "The results showed that the expression of both CSF1 and KIT was significantly downregulated in breast cancer tissues compared to non-tumor samples." (PMID 37445965, 2023). "The expression levels of the CSF1 and KIT genes were compared between breast cancer and adjacent non-tumor tissues from patients, using original published data available in the GEPIA database." (PMID 37445965, 2023). "This analysis indicated that the mean expression of CSF1 and CSF1R genes did not vary significantly (assessed by One-way ANOVA analysis) among breast cancer subtypes in either cell lines or in tumors samples." (PMID 22096574, 2011). "Indeed, several inhibitors of the CSF1-CSF-1R or CCR2-CCL2 signalling axes have shown therapeutic benefits in mouse models of pancreatic and breast cancer, both in combination and without chemotherapeutical agents and in clinical settings." (PMID 28210073, 2017).